RB1 (RB transcriptional corepressor 1)
Diseases named in the same sentence as RB1 in open-access papers (continued):
Sharing a sentence is not in itself a finding about the gene and the disease.
nasopharyngeal carcinoma (4 papers, 2019 to 2022). A carcinoma arising from the nasopharyngeal epithelium. "Through targeting RB1 and triggering the Wnt/β-catenin pathway, miR-215 promotes nasopharyngeal carcinoma progression." (PMID 36467881, 2022). "Additionally, it has been reported that RB1 affects the PI3K/Akt pathway to promote nasopharyngeal carcinoma EMT." (PMID 35969010, 2022).
pancreatic adenocarcinoma (4 papers, 2012 to 2026).
papilloma (4 papers, 2013 to 2022). A benign epithelial neoplasm that projects above the surrounding epithelial surface and consists of villous or arborescent outgrowths of fibrovascular stroma. "Experimental MmuPV1 infection of a mouse strain that expresses an LXCXE protein binding-deficient RB1 mutant causes the formation of papillomas." (PMID 34465025, 2021). "Experimental infection of mice with MmuPV1 expressing an E7 mutant that is defective for binding to RB1 caused delayed onset, lower incidence, and smaller sizes of papillomas." (PMID 34465025, 2021). "Together, the assessments of the incidence of papillomas, the time of onset of papillomas, and the size of papillomas at the endpoint all indicate that the interaction between MmuPV1 E7 and Rb1 quantitatively correlates with MmuPV1’s ability to cause papillomatosis." (PMID 34465025, 2021). "Papillomas caused by the MmuPV1 E7D90A quasivirus were significantly smaller than those caused by MmuPV1 (MmuPV1 versus MmuPV1 E7D90A, P = 0.003, two-sided t test), indicating that the loss of E7’s ability to interact with Rb1 correlates with reduced size of MmuPV1-induced papillomas." (PMID 34465025, 2021).
primitive neuroectodermal tumor (4 papers, 2016 to 2025). A malignant neoplasm that originates in the neuroectoderm. "Patients with germline mutations in RB1 have a risk of about 5% of developing intracranial midline primitive neuroectodermal tumors." (PMID 28292093, 2016).
skin cancer (4 papers, 2014 to 2024).
thymic carcinoma (4 papers, 2015 to 2023). Thymic carcinoma (TC) is a type of thymic epithelial neoplasm characterized by a high malignant potential. "RB1 expression and RB1 phosphorylation have been reported in most thymic epithelial tumors, including thymic carcinomas." (PMID 38201593, 2023).
type 2 diabetes (4 papers, 2013 to 2023). "Specifically, Rb1 and Rg1 treatment improved PPARγ expression and decreased total cholesterol, triglyceride, and glucose levels in peripheral blood of patients with type 2 diabetes." (PMID 23520555, 2013).
abdominal aortic aneurysm (3 papers, 2021 to 2023). Enlargement and ballooning of the vessel that supplies arterial blood to the abdomen, pelvis and legs. "Rb1 was more effective than Rg1 in mitigating vascular smooth muscle dysfunction in the presence of angiotensin 2-induced abdominal aortic aneurysm and inhibiting vascular inflammatory action in the coronary artery endothelium." (PMID 37765046, 2023).
Alpha-thalassemia (3 papers, 2021 to 2024). Alpha-thalassemia is an inherited hemoglobinopathy characterized by impaired synthesis of alpha-globin chains leading to a variable clinical picture depending on the number of affected alleles.
Alzheimer disease (3 papers, 2016 to 2020). A progressive, neurodegenerative disease characterized by loss of function and death of nerve cells in several areas of the brain leading to loss of cognitive function such as memory and language. "Interestingly, tumour suppressor gene RB1 (retinoblastoma 1) is a high impact gene in ER-negative breast cancer and Alzheimer's disease (AD) severe." (PMID 26975659, 2016).
anaplastic astrocytoma (3 papers, 2003 to 2017). "A correlation between alterations of these genes and poor prognosis has been observed for RB1 in non‐small‐cell lung cancers 37 and anaplastic astrocytoma 38, and increased mRNA expression of TERT was previously reported as a poor prognostic marker in breast 39 and lung 40 cancers." (PMID 27873319, 2017).
anaplastic oligodendroglioma (3 papers, 2009 to 2025). A WHO grade III oligodendroglioma with focal or diffuse malignant morphologic features (prominent nuclear pleomorphism, mitoses, and increased cellularity). "Patient I, which was diagnosed with anaplastic oligodendroglioma, had CTCs with mutation in the RB1 gene, which results in a frameshift with premature stop codon." (PMID 31466397, 2019).
angiosarcoma (3 papers, 2013 to 2018). A malignant tumor arising from the endothelial cells of the blood vessels.
Anxiety (3 papers, 2017 to 2019). Intense feelings of nervousness, tension, or panic often arise in response to interpersonal stresses. "However, we found that MPTP or Rb1 showed no obvious effects on the total distance, movement speed, number of entries to open arms and the time spent in the open arms, suggesting that Rb1 may influence memory deficiencies rather than anxiety of MPTP-treated mice." (PMID 31314744, 2019).
bone metastasis (3 papers, 2019 to 2022). Transfer of a neoplasm from its primary site to bones. "Low expression of VIM and RB1 (p = 0.020) but high ESR1 expression (p = 0.020) was identified in CTCs’ patients who had bone metastasis." (PMID 31817194, 2019). "There was a statistical difference in the number of RB1 gene mutations in the bone metastasis group compared with the no bone metastasis group." (PMID 34799997, 2022). "In patients without bone metastasis, patients whose RB1 expression were low tended to have faster time to CRPC (mean 15 months, 95% CI: 8.9–12.1) than those who presented with high expression (mean 36.4, 95% CI: 29.2–43.7) (p = 0.017)." (PMID 33299560, 2020).
Cerebral ischemia (3 papers, 2019 to 2025). Restriction of arterial blood supply to the brain associated with insufficient oxygenation to support the metabolic requirements of the tissue. "In present study, high expression of GLUT1 by SSS should make Rb1 easy to pass BBB after cerebral ischemia." (PMID 31065240, 2019). "Several studies have revealed that Rb1 regulates the expression of BDNF and activates neurogenesis in rats with experimental cerebral ischemia." (PMID 34658847, 2021).
chronic myeloid leukemia (3 papers, 2021 to 2023). "KEGG analysis in the BaF3-T315 cells showed that the chronic myeloid leukemia signaling pathway (genes such as Cdk4, Tgfbr1, Gadd45b, Mdm2, Gadd45g, Polk, Rb1, Ctbp1, and Cdkn2a were enriched) was involved in the I13 treatment." (PMID 37124196, 2023).
colorectal adenocarcinoma (3 papers, 2016 to 2023). The most common type of colorectal carcinoma. "In addition, a recent report shows that Histone Deacetylase 1 and 2 (HDAC1 and 2) have a reciprocal relationship to RB1 and are able to reduce ABCB1 and ABCC2 gene and protein expression in colorectal adenocarcinoma and carcinoma cell lines." (PMID 26799285, 2016).
colorectal tumour (3 papers, 1994 to 2016).
developmental delay (3 papers, 2020 to 2024). "In conclusion, this study adds novelties regarding the genotype-phenotype correlation in 13q deletion syndrome including RB1, defining a new key region for developmental delay." (PMID 34573300, 2021).
Down syndrome (3 papers, 2018 to 2025). "In this study, we focused on syndromic disorders caused by seven tumor suppressor genes: FH, NF1, PTCH1, RB1, STK11, and TSC1/2." (PMID 40702147, 2025).
ductal adenocarcinoma (3 papers, 2015 to 2023).
embryonic carcinoma (3 papers, 2010 to 2020). "Both LOHs of the CDKN2A were found in nonseminomas with a yolk sac tumor component, and both LOHs of the RB1 were found in nonseminomas with an embryonal carcinoma component." (PMID 22933911, 2010). "Furthermore, both LOHs of the RB1 were found in nonseminomas with an embryonal carcinoma component." (PMID 22933911, 2010).
ependymoma (3 papers, 2003 to 2021). A WHO grade II, slow growing tumor of children and young adults, usually located intraventricularly. "CDK4, CCND1, and RB1 were found to be upstream regulators in the cell cycle process; therefore, CDK4 and CCND1 seem to be the main targets in ependymomas." (PMID 33271970, 2020).
gastric tumor (3 papers, 2011 to 2024). "Furthermore, RB1 silencing with shRNA in gastric tumour cells resulted in increased IL-8 levels." (PMID 38862740, 2024).
gliosarcoma (3 papers, 2019 to 2021). A rare histological variant of glioblastoma (WHO grade IV) characterized by a biphasic tissue pattern with alternating areas displaying glial and mesenchymal differentiation (WHO). "Other mutations seen in high frequency in this particular analysis of gliosarcoma include TERT promoter, CDK2NB, RB1, and STAG2." (PMID 34504233, 2021). "Somatic coding indels in NF1 (3/10 gliosarcoma samples), PTEN (2/10), RB1 (2/10) and PIK3R1 (2/10) genes with a minimal penetration of 15% (within a given sample) were found in 5/10 samples." (PMID 30818875, 2019). "Gliosarcomas are similar to primary GBM in their molecular profiles and exhibit a similar rate of NF1, RB1 and PTEN alterations." (PMID 30818875, 2019).
hereditary cancer syndromes (3 papers, 2016 to 2025). "Absence of germline RB1 mutations or other hereditary cancer syndromes implicates treatment‐related factors (chemotherapy/radiotherapy) as the primary driver of sequential malignancies." (PMID 41307228, 2025).
Hyperglycemia (3 papers, 2015 to 2023). An increased concentration of glucose in the blood. "In our study, we found that Rb1 could reduce the suppression of AMPK caused by hyperglycemia." (PMID 34712140, 2021). "Nevertheless, the effect of Rb1 on vascular diseases under hyperglycemia is unclear, whose contributing molecular mechanisms remain to be elucidated." (PMID 34712140, 2021). "The finding that Rb1 is effective as a preventive and therapeutic intervention for hyper-vasoconstriction induced by HG and ED in rat aorta provides a potential rationale for clinical trials aimed at evaluating the efficacy of Rb1 in patients with both hyperglycemia and ED." (PMID 37765046, 2023). "Rb1 is expected to have therapeutic potential in diseases accompanied by hyperglycemia and ED." (PMID 37765046, 2023).
hyperlipidemia (3 papers, 2021 to 2024). "Based on the results summarized above, we predicted that to suppress hyperlipidemia, Rb1 modulates gut microbiota to increase the level of phosphatidylcholine in glycerophospholipid metabolism, decreasing TC." (PMID 33744860, 2021). "The comprehensive multiomics analysis was valuable for elaborating the functional mechanism by which Rb1 reduces hyperlipidemia." (PMID 33744860, 2021). "Additionally, Rb1 stimulates skin wound healing through a sphingolipid-1-phosphate-dependent mechanism and inhibits hyperlipidemia by regulating the synthesis and breakdown of phosphatidylcholine in GPL metabolism while also modulating the gut microbiota." (PMID 39403214, 2024). "Results from fecal transplanted germ-free mice suggest that to suppress hyperlipidemia, Rb1 regulates gut microbiota by regulating the synthesis and decomposition of phosphatidylcholine in glycerophospholipid metabolism, which in turn decreases serum total cholesterol." (PMID 33744860, 2021). "However, the mechanism by which Rb1 relieves hyperlipidemia remains unclear." (PMID 33744860, 2021).
influenza (3 papers, 2017 to 2023). An acute viral infection of the respiratory tract, occurring in isolated cases, in epidemics, or in pandemics; it is caused by serologically different strains of viruses (influenzaviruses) designated A, B, and C, has a 3-day incubation period, and usually lasts for 3 to 10 days. "In summary, we hypothesize that Rb1 has an immune-enhancing effect, correcting the species richness and diversity of gut microbiota in influenza vaccines." (PMID 37868069, 2023). "It is interesting that influenza-induced pathological changes in animal lungs existed during the acute course of infection, indicating the capability of virus to establish disease in the presence of Rb1; however, the magnitude of infection was lower." (PMID 28187149, 2017). "We observed that Rb1, if incubated with virus for less than one hour, did not protect animals against lethal influenza infection (data not shown)." (PMID 28187149, 2017).
laminopathies (3 papers, 2011 to 2014). "Thus, this study begins to fill in the missing link between the loss of RB1 activity in interphase and aberrant events in mitosis observed in other laminopathies." (PMID 21464947, 2011). "Our data indicate that these mitotic defects are associated with low levels of activated RB1 and CAPD3, as well as other defects in the mitotic spindle checkpoint, suggesting a new role for RB1 in the mitotic defects of laminopathies." (PMID 21464947, 2011).
Lewis lung carcinoma (3 papers, 2014 to 2025). "In this work, the cytotoxicity of free PPD, Rb1 NPs, and Rb1/PPD NPs were evaluated using the Cell Counting Kit-8 (CCK-8) assay with murine Lewis lung carcinoma (LLC) cells." (PMID 29473838, 2018).
mental retardation (3 papers, 2019 to 2024). "Large deletions that include the RB1 gene lead to widely variable clinical phenotypes, including intellectual disability, referred to as 13q deletion syndrome." (PMID 31806026, 2019).
ovarian teratoma (3 papers, 2015 to 2021). A non-seminomatous germ cell tumor arising from the ovary. "A deficiency of Retinoblastoma 1 (Rb1) or Forkhead box O3a (Foxo3a) has been shown to cause oocyte abnormality and ovarian teratoma." (PMID 29378702, 2018). "Here, we report development of a novel mouse model in which conditional inactivation of the tumor suppressor gene Rb1 in oocytes leads to the formation of ovarian teratomas (OTs)." (PMID 26176933, 2015). "Previous studies in mice revealed that premature exhaustion of the follicle pool occurs following conditional inactivation of Rb1 in granulosa cells specifically, but formation of ovarian teratomas was not reported." (PMID 26176933, 2015).
pancreatic NEN (3 papers, 2021 to 2024).
parathyroid tumors (3 papers, 2014 to 2024). "Detection of widespread LOH of the RB1 locus in parathyroid carcinoma with loss of its corresponding protein pRB prompted the investigation of pRB expression in parathyroid tumors—but with divergent results both concerning staining outcomes as well as LOH events." (PMID 33269427, 2021).
prostatic small cell carcinoma (3 papers, 2015 to 2023). "It has been postulated that differentiated NE-like cells may progress to small-cell prostate carcinoma (SCPC) through the accumulation of additional genetic alterations, such as loss of RB1, MYCN, and AURKA amplification." (PMID 37740039, 2023).
Stroke (3 papers, 2014 to 2018). Sudden impairment of blood flow to a part of the brain due to occlusion or rupture of an artery to the brain. "In order to confirm the importance of Rb in cerebral ischemic injury and determine the protective effects of BBR during stroke, RB1 knockdown stable cell lines were constructed using lentiviral vectors." (PMID 24603897, 2014).
T-cell lymphoma (3 papers, 2021 to 2022). "Functional annotation analysis of the genes within the most susceptible (top 5%) genomic regions in RB1 KO cells identified cancer and disease-related categories, including “Chemical Carcinogenesis” and “T-cell lymphoma and Cutaneous Skin Neoplasms”." (PMID 34983823, 2022).
thymic epithelial tumors (3 papers, 2015 to 2023). "Inactivating mutations and deletions of RB1 have been described in thymic epithelial tumors but appear relatively uncommon." (PMID 38201593, 2023).
Wilms tumor (3 papers, 2021 to 2025). An embryonal neoplasm characterized by the presence of epithelial, mesenchymal, and blastema components. "N-myc, WT1, and RB1 genes are associated with NB, nephroblastoma, RB, and other tumors, respectively." (PMID 33259778, 2021).
anemia (2 papers, 2009 to 2011). A reduction in the number of red blood cells, the amount of hemoglobin, and/or the volume of packed red blood cells. "Mice with homozygous disruption of the RB1 alleles resulted in an overall normal development but had lethal anemia, suggesting a critical role of the RB1 gene in erythropoiesis." (PMID 21851601, 2011).
asthma (2 papers, 2020 to 2024). "For the remaining genes (airway fibroblasts: HOOK2 and HOXA7; parenchymal fibroblasts: HOXA5, HOXA6, HOXA-AS3, RB1 and NR2F1-AS1), there was no differential gene expression between donors with and without asthma." (PMID 33008450, 2020).
autoimmune disease (2 papers, 2022 to 2023). A disorder resulting from loss of function or tissue destruction of an organ or multiple organs, arising from humoral or cellular immune responses of the individual to their own tissue constituents.